NR4A1 (nuclear receptor subfamily 4 group A member 1)
Diseases named in the same sentence as NR4A1 in open-access papers (continued):
Sharing a sentence is not in itself a finding about the gene and the disease.
endometrioid endometrial carcinoma (3 papers, 2015 to 2025). "Although NR4A1 expression promotes the growth of these tumors, NR4A1 regulated by long non-coding RNAs activates the apoptosis signaling pathway and inhibits the progression of endometrioid endometrial carcinoma." (PMID 40666103, 2025).
experimental autoimmune encephalomyelitis (3 papers, 2023 to 2025). An autoimmune demyelinating disease of the central nervous system that is produced experimentally in animals by the injection of homogenized brain or spinal cord in Freund's adjuvant. "In addition, knockout of NR4A1 increases in the number of infiltrating myeloid cells and activated microglia during the early prodromal phase of experimental autoimmune encephalomyelitis." (PMID 40746844, 2025). "NR4A1-deficient myeloid cells exhibit increased production of norepinephrine, and this resulted in acceleration of experimental autoimmune encephalomyelitis (AEA) and increased lumbar spinal cord Th expression." (PMID 40871737, 2025).
injury (3 papers, 2022 to 2025). Damage inflicted on the body as the direct or indirect result of an external force, with or without disruption of structural continuity. "In this study, we employed NR4A1−/− mice to decipher the role of NR4A1 in the onset and progression of acute lung injury with a focus on mitochondrial damage and necroptosis." (PMID 35222801, 2022). "Overall, these data support a role for antioxidative and anti-inflammatory actions by NR4A1 deletion in LPS-induced acute lung injury." (PMID 35222801, 2022). "In conclusion, the findings decode a previously unidentified role for a myeloid‐TLR4 dependent Nr4a1/Ear2 negative feedback mechanism in macrophage‐mediated progressive renal injury, implying that activation of Nr4a1‐Ear2 axis can be a novel and effective immunotherapy for anti‐GBM cGN." (PMID 35484716, 2022).
ischemia (3 papers, 2015 to 2024). A hypoperfusion of the BLOOD through an organ or tissue caused by a PATHOLOGIC CONSTRICTION or obstruction of its BLOOD VESSELS, or an absence of BLOOD CIRCULATION. "We first explored the putative effect of NR4A1 on the expression profiles of inflammatory factors after ischemia." (PMID 37486903, 2023).
liver disease (3 papers, 2022 to 2024).
nonalcoholic fatty liver disease (3 papers, 2020 to 2024). "At the same time, the factor member 1 of nuclear receptor subfamily group 4A (Nr4A1) related to Nrf2 is linked to the prevention of non-alcoholic fatty liver disease by hyperoside." (PMID 35566359, 2022).
pancreatic adenocarcinoma (3 papers, 2014 to 2024). "We tested whether MALAT1 expression and NR4A1-downstream RE accessibility were strongly correlated in cancer types, such as BRCA, versus low- or no-correlation cancers, such as pancreatic adenocarcinoma (PDAC)." (PMID 38791553, 2024).
prostate adenocarcinoma (3 papers, 2023 to 2025). "12-O-tetradecanoylphorbol 13-acetate induces the formation of a heterodimer of NR4A1 with RXRα (NR4A1/RXRα heterodimer), leading to the translocation of NR4A1/RXRα heterodimer to mitochondria in the human prostate adenocarcinoma cell line LNCaP." (PMID 40746844, 2025).
renal carcinoma (3 papers, 2019 to 2021). A carcinoma arising from the epithelium of the renal parenchyma or the renal pelvis. "ACHN and 786-O renal cell lines showed that the Nr4a1 antagonists DIM-C-pPhOH and DIM-C-pPhCO2Me decreased cell numbers in a dose dependent manner and decreased ACHN xenograft size, suggesting that Nr4a1 also promotes renal cancer proliferation." (PMID 31683815, 2019).
alveolar rhabdomyosarcoma (2 papers, 2022 to 2024). A rapidly growing malignant mesenchymal neoplasm. "In alveolar rhabdomyosarcoma (ARMS), the orphan nuclear receptor 4A1 (NR4A1) is responsible for G9a overexpression by complexing with the Sp1 transcription factor (Sp1) and occupying the -511 GC-rich region of the G9a promoter." (PMID 35740522, 2022).
Alzheimer disease (2 papers, 2015 to 2022). A progressive, neurodegenerative disease characterized by loss of function and death of nerve cells in several areas of the brain leading to loss of cognitive function such as memory and language. "For example, NR4A1, whose promoter overlaps with DMRs, has been implicated in several diseases, such as SZ, Alzheimer’s disease as well as cancer." (PMID 26462620, 2015).
brain injury (2 papers, 2023 to 2024). Acute and chronic (see also brain INJURIES, CHRONIC) injuries to the brain, including the cerebral hemispheres, CEREBELLUM, and brain STEM. "Previous studies have confirmed that Nr4a1-deficiency caused a significant decrease in Ly6C- monocyte, which might also affect the outcome of ischemic brain injury in mice." (PMID 37486903, 2023).
cocaine addiction (2 papers, 2017 to 2020). "The regulatory effects of Nr4a1 on cocaine-induced gene transcription and its role in attenuating cocaine-induced behaviors make it a promising therapeutic target in cocaine addiction." (PMID 31980629, 2020). "Herein, we established Nr4a1 as a key regulator of persistent gene transcription during cocaine abstinence and as a promising therapeutic target for cocaine addiction." (PMID 31980629, 2020). "Finally, the availability of a small molecule agonist that crosses the blood-brain barrier to activate Nr4a1, in vivo, lends promise to the clinical relevance of our findings, and the potential of Nr4a1 as a therapeutic target to combat cocaine addiction." (PMID 31980629, 2020). "Our results further demonstrated that Nr4a1 persistently increased while Nr4a2 and Nr4a3 showed transient changes after cocaine withdrawal, indicating their different roles in different stages of cocaine addiction." (PMID 28386228, 2017).
head and neck cancer (2 papers, 2022 to 2025). A primary or metastatic malignant neoplasm affecting the head and neck. "In head and neck malignant tumors, overexpression of HDAC9 promotes carcinogenesis by targeting the transcription factor MEF2D and the proapoptotic MEF2 target, NR4A1/Nur77." (PMID 40145017, 2025).
hematoma (2 papers, 2019 to 2023). A hematoma is a collection of blood from a vascular structure into an extravascular space. "To confirm that the observed effects with celastrol treatment were indeed mediated through NR4a1, we treated NR4a1 cKO mice with celastrol after ICH induction and evaluated hematoma clearance and alternative activation of MDMs in the hemorrhagic brains (Fig EV5B)." (PMID 37965920, 2023). "Furthermore, the knockdown of Nr4a1 significantly increased the expression of p-NF-κB p65, IL-1β, TNF-α, and MMP-9 with a decrease of ZO-1, occludin, and Lama5 in the peri-hematoma tissue." (PMID 31660977, 2019).
hyperandrogenic (2 papers, 2012 to 2020). "This information led us to raise another query: does NR4A1 level increases because of the inflammatory mechanism as a triggering factor or due to hyperandrogenism in PCOS or both?" (PMID 32181090, 2020). "As PCOS patients generally have hyperandrogenism, NR4A1 overexpresses in PCOS." (PMID 32181090, 2020).
intracerebral hemorrhage (2 papers, 2019 to 2024). A cerebrovascular disorder characterized by bleeding into one or both cerebral hemispheres including the basal ganglia and the cerebral cortex. "Creb has been implicated in neuroinflammation amelioration and blood-brain barrier stabilization post-intracerebral hemorrhage through NR4a1 regulation." (PMID 38834564, 2024).
myeloid leukemia (2 papers, 2022 to 2024). A clonal proliferation of myeloid cells and their precursors in the bone marrow, peripheral blood, and spleen. "NR4A1 and NR4A3 also function as tumor suppressors of myeloid leukemia, and downregulation of NR4A1 and NR4A3 expression is a common feature of the leukemic blast." (PMID 38539632, 2024). "Together, our findings demonstrate a tight association between impaired differentiation status and NR4A3 downregulation in myeloid leukemias, providing a plausible mechanistic explanation of how myeloid leukemogenesis might occur upon concurrent downregulation of NR4A1 and NR4A3." (PMID 36040481, 2022).
myocardial inflammation (2 papers, 2024 to 2025). "Specifically, NR4A1 exacerbated myocarditis-induced injury following I/R and mediated the dysregulation of mitochondrial." (PMID 39247823, 2024).
pheochromocytoma (2 papers, 2012 to 2016). "NR4A1 (also known as Nur77, NGFI-B or TR3) belongs to a superfamily of orphan nuclear receptors and was originally isolated as an immediate-early response gene induced by a nerve growth factor in a pheochromocytoma cell line, PC12." (PMID 22792320, 2012).
pneumonia (2 papers, 2021 to 2025). An acute, acute and chronic, or chronic inflammation focally or diffusely affecting the lung parenchyma, caused by an infection in one or both of the lungs (by bacteria, viruses, fungi, or mycoplasma.). "A deeper understanding of how Nr4a1 influences neutrophil recruitment, activation, and effector functions compared to other immune cells is critical for optimizing Nr4a1-directed pneumonia treatment strategies." (PMID 40114913, 2025). "In addition to investigating the differential roles of Nr4a1 in distinct immune cell populations, it is crucial to determine whether the Nr4a1-mediated immune response is pathogen-specific in pneumonia." (PMID 40114913, 2025). "Thus, we sought to investigate whether Nr4a1 was critical for pulmonary immunity to pneumonia using the murine model of Klebsiella pneumoniae." (PMID 40114913, 2025).
Prader-Willi syndrome (2 papers, 2016 to 2023). "Finally, Nr4a1 may serve as a potential drug target for SNRPN-related neurodevelopmental disabilities, including Prader-Willi syndrome (PWS) and autism spectrum disorders (ASDs)." (PMID 27430727, 2016).
sarcoidosis (2 papers, 2020 to 2022). Sarcoidosis is a multisystemic disorder of unknown cause characterized by the formation of immune granulomas in involved organs. "Loss of NR4A1 exacerbates organ fibrosis by dysregulating TGF-β pathway a mechanism potentially related to sarcoidosis lung progressive disease." (PMID 36388923, 2022). "Only six genes (ADAMTS1, HSPB6, NR4A1, CXCL2, NPR1, ITGA9) were exclusively dysregulated in both lung and lymph node in sarcoidosis granulomas but not in CM or TB." (PMID 33276795, 2020).
Seizure (2 papers, 2016 to 2017). A seizure is an intermittent abnormality of nervous system physiology characterized by a transient occurrence of signs and/or symptoms due to abnormal excessive or synchronous neuronal activity in the brain. "Therefore, we proposed that the NR4A1 pathway could play an important role in regulating epileptic seizures and may be involved in the development of refractory epilepsy in humans." (PMID 27876882, 2016).
subarachnoid hemorrhage (2 papers, 2020 to 2022). A serious neurological disorder characterized by intracranial hemorrhage into the subarachnoid space. "Although these studies did not link the cerebral vasculature to Nr4a1 signaling, it is important to note that trauma was modeled by inducing subarachnoid hemorrhage." (PMID 31907354, 2020).
temporal lobe epilepsy (2 papers, 2020 to 2022). A localization-related (focal) form of epilepsy characterized by recurrent seizures that arise from foci within the temporal lobe, most commonly from its mesial aspect. "DNA methylation of the NR4A1 gene has also been used as an a priori reference among individuals with and without temporal lobe epilepsy, and revealed components associated with differences in age of onset and poor cognitive ability." (PMID 35968362, 2022).
acute promyelocytic leukemia (1 paper, 2022). An aggressive form of acute myeloid leukemia (AML), characterized by arrest of leukocyte differentiation at the promyelocyte stage, due to a specific chromosomal translocation t(15;17) in myeloid cells.
adenovirus infection (1 paper, 2023). "Also, nuclear receptor subfamily 4, group A, member 1 (NR4A1) have been reported to be among the DEGs that showed decrease expression during the progression of an adenovirus infection." (PMID 37351013, 2023).
allergic rhinitis (1 paper, 2025). Inflammation of the nasal mucous membranes caused by an IgE-mediated response to external allergens. "A recent study showed that the flavonoid baicalein activated NR4A1 to inhibit ovalbumin-induced allergic rhinitis in mice and it is likely that this response was also due, in part, to baicalein acting as an NR4A1 ligand." (PMID 40871737, 2025).
anxiety depression (1 paper, 2024). "Six core mRNAs on which ZZCD works for anxiety depression were obtained by constructing PPI network: Fos, Junb, Egr2, Dusp1, Nr4a1, and Btg2." (PMID 37905694, 2024).
atopic dermatitis (1 paper, 2026). "Our findings establish a causal relationship between specific gut bacteria (Eubacterium eligens group) and atopic dermatitis risk while identifying seven key bridging genes (AKR1C2, GALE, GGH, NR4A1, PLA2G4B, TYMS) that connect gut microbial metabolites to skin pathology." (PMID 41556698, 2026). "In the atopic dermatitis context, NR4A1 dysfunction may prevent effective inflammation termination, establishing chronic inflammatory states." (PMID 41556698, 2026). "For tamoxifen, its combination with NR4A1 was chosen for simulation (binding energy of −6.5 kcal/mol) primarily based on the critical regulatory role of NR4A1 in Th2-type immune responses, which are highly relevant to the pathogenesis of atopic dermatitis." (PMID 41556698, 2026). "Also, the discovery of tamoxifen’s interaction with NR4A1 provides new strategic options for atopic dermatitis treatment." (PMID 41556698, 2026).
bacterial pneumonia (1 paper, 2025). Acute infection of the lung parenchyma caused by bacteria (e.g., Streptococcus pneumoniae, Haemophilus influenzae, Chlamydia pneumoniae, Mycoplasma pneumoniae, and Legionella pneumophila). "This unique cell-specific function of Nr4a1 in neutrophils suggests that targeting neutrophil-specific Nr4a1 could be a promising approach developing immunotherapies against bacterial pneumonia." (PMID 40114913, 2025).
cataract (1 paper, 2023). Partial or complete opacity of the crystalline lens of one or both eyes that decreases visual acuity and eventually results in blindness. "Compared with the ARC group, the levels of CTGF, FOS, CAV1, CYR61, ICAM1, EGR1, and NR4A1 in the anterior capsule of PACG patients with cataracts were upregulated, which was consistent with the sequencing data." (PMID 37131205, 2023).
Cerebellar atrophy (1 paper, 2020). Cerebellar atrophy is defined as a cerebellum with initially normal structures, in a posterior fossa with normal size, which displays enlarged fissures (interfolial spaces) in comparison to the foliae secondary to loss of tissue. "Higher methylation of NR4A1 was also related to reduced GMV in cerebellum and lower FA in MCP, consistent with cerebellar atrophy found in TLE in numerous studies." (PMID 32760244, 2020).
cervicitis (1 paper, 2024). An acute or chronic inflammatory process that affects the cervix. "Regarding gene expression, there was an increase in the expression of NR4A1 in women with cervicitis compared to women who exhibited CIN I and CIN III." (PMID 39639963, 2024). "It was observed that the receptor NR4A1 was significantly overexpressed in cases of cervicitis when compared to CIN 1 and CIN 3 (p = 0.0378)." (PMID 39639963, 2024).
chronic hepatitis (1 paper, 2015). An active inflammatory process affecting the liver for more than six months. "Moreover, NR4A1 and NR2F1 are soluble nuclear hormone receptors that regulate liver development, differentiation and function, and are implicated in the modulation of the hepatocyte priming and proliferation in regenerating liver, chronic hepatitis and HCC development." (PMID 26226632, 2015).
chronic myeloid leukemia (1 paper, 2020). "In contrast, forced expression of NR4A1 had no impact on MYC expression in K562 chronic myeloid leukemia cells, which which express high levels of MYC but do not display SE activation at this genomic region." (PMID 32071334, 2020).
cocaine use disorder (1 paper, 2022). A substance-related disorder that involves the recurring use of cocaine despite negative consequences. "This study defined the epigenetic regulation of Nr4a1 in reward brain regions in male and female mice following cocaine, and, thus, shed light on the biological relevance of sex to cocaine use disorder." (PMID 36130958, 2022).
cognitive (1 paper, 2025). "In the C57BL/6J mice with YAP1 knockdown, Nr4a1 expression was either knocked down or inhibited with DIM-C to examine the impact of Nr4a1 on tau phosphorylation and cognitive deficits." (PMID 40468463, 2025).
coronary atherosclerosis (1 paper, 2020). Atherosclerosis of the coronary vasculature. "In inflammation-associated diseases like coronary atherosclerosis, tumor and neurodegenerative disease, NR4A1 was proved to be up-regulated and approaches targeting NR4A1 could partially ameliorate disease progression." (PMID 32258036, 2020).
crescentic glomerulonephritis (1 paper, 2022). A histopathologic term for a pattern of diseases characterized by extensive crescent formation in the glomeruli; patients present clinically with rapid deterioration of renal function, and possible progression to end-stage renal failure within weeks or months. "In this study, the authors discover that deletion of myeloid TLR4 inhibits immunologically mediated crescentic glomerulonephritis (cGN) by inducing a novel Nr4a1/Ear2‐expressing anti‐inflammatory macrophages while suppressing M1 proinflammatory responses." (PMID 35484716, 2022).
diaphragm (1 paper, 2025). "CsnB treatment increased Nr4a1 expression (1.128 ± 0.113 vs. 0.490 ± 0.084, p < 0.0001), mitigating prolonged MV‐induced diaphragm fibrosis and dysfunction but not atrophy (938.1 ± 116.2 vs. 754.7 ± 155.5, p = 0.1079)." (PMID 41332397, 2025).
energy metabolism disorder (1 paper, 2024). "On the contrary, higher levels of nuclear receptor subfamily 4 group A member 1 (NR4A1) induced by ox-LDL in endothelial cells triggered excessive Parkin-dependent mitophagy, whereas NR4A1 deletion was shown to protect endothelial cells from energy metabolism disorder and apoptosis." (PMID 38812059, 2024).
follicular thyroid carcinomas (1 paper, 2022). "Although a previous study has reported that lithium treatment-induced upregulation of NR4A1 in follicular thyroid carcinomas inhibited cell growth and triggered apoptosis, the contribution of NR4A1 to PTC pathogenesis has yet to be elucidated." (PMID 35110542, 2022).
fungal infection (1 paper, 2020). "Consequently, Nr4a1-/- mice displayed dramatically diminished Ly6Clow monocyte recruitment to the brain after fungal infection." (PMID 32101593, 2020).
glomerulonephritis (1 paper, 2019). A renal disorder characterized by damage in the glomeruli. "Further evidence that pMo contribute to the kidney pathology is suggested by the recent finding that chimaeric mice devoid of pMo, which were generated by injecting liver cells from the foetus of ABIN1 KO × Nr4a1 KO mice into irradiated WT mice, did not develop glomerulonephritis." (PMID 31694920, 2019).
glucose metabolism disorders (1 paper, 2021). "Some studies have found that higher levels of NR4A1 are closely related to glucose metabolism disorder, renal insufficiency, renal hypertrophy, and fibrosis, and contribute to the occurrence and development of DKD." (PMID 35186975, 2021).